TLR4 (toll like receptor 4)
Diseases named in the same sentence as TLR4 in open-access papers (continued):
Sharing a sentence is not in itself a finding about the gene and the disease.
tumor (continued). "In addition, PSP were also evaluated for its activation of TLR4, TLR4-downstream molecules (TRAF6, NF-κB and AP-1) in spleens of tumor-bearing C57BL/10J (TLR4+/+) and C57BL/10ScCr (TLR4-/-) mice." (PMID 26032186, 2015). "TLR4 depletion inhibited HepG2.2.15 cell colony formation and tumor growth in nude mice." (PMID 26514586, 2015). "TAMs could mediate EMT of tumor cells and promote the tumor progression through the TLR4/IL-10 signaling pathway." (PMID 26161392, 2015). "Sal-YB1 could significantly upregulate Toll-like receptor 4 (TLR4) expression in tumor tissues by flow cytometry." (PMID 26286454, 2015). "We propose that TLR4 on the surface of these PCMs may play a role in the interaction between the epithelial and stromal compartments to promote neoplasia." (PMID 24887394, 2014). "Although detailed mechanisms and regulation of the TLR4 functions in tumor pathogenesis remain to be elucidated, TLR4 may be a promising target for the development of anticancer agents in the future." (PMID 24959291, 2014). "The expressions of TLR4 and NF-κB p65 in the tumor samples were detected by Western blotting." (PMID 25225511, 2014). "TLR4 may be responsible for uncontrolled tumor growth under LPS stimulation in human colon environment." (PMID 24390484, 2014). "The TLR4 pro-tumorogenic activity is mainly due to its expression on tumor cells where it mediates resistance of tumor cells to damage induced by cytotoxic T lymphocytes, but triggering of TLR4 expressed on immune cells is also important in tumor development and progression." (PMID 25309546, 2014). "Thus, novel TLR4 agonists are needed for use as adjuvants in tumor and infectious disease vaccine production, especially when using DC-based vaccination strategies." (PMID 25102137, 2014). "Dying tumor cells release HMGB1 that has been shown to activate TLR4 on DCs." (PMID 24904578, 2014). "TLR4 staining scores were recorded in the tumor stroma and stratified by tumor grade as follows: well-differentiated = 3.91, moderately-differentiated = 3.02, poorly-differentiated = 3.59, undifferentiated = 3.64 (ANOVA comparing all four categories, p = 0.0005)." (PMID 24887394, 2014). "After establishing the significant effects of TLR4 stimulation by LPS in MDA-MB-231 and MCF-7 cells in vitro, we then investigated whether TLR4 stimulation also promoted tumorigenicity and metastasis in a mouse tumor model." (PMID 25299052, 2014). "TLR-2 and TLR-4 mRNA and protein expression have been reported in thyroid cells in vitro, and these TLRs promote tumor progression in cancer by activating cell proliferation and taking part in tumor invasion." (PMID 25328756, 2014). "The demonstration that paclitaxel can bind to TLR4/MD-231 and therefore activate NF-κB could explain why tumor growth was observed during paclitaxel treatment of patient with advanced EOC4." (PMID 24452475, 2014). "Although TLR4 is expressed in numerous non-immune cells and tumor cells, the functional association of TLR4 with tumor progression requires further elucidation." (PMID 24959291, 2014). "Since TLR4 is also expressed on T-cells and potentiates T cell activation, TLR4 signaling of T cells activated by Ad vectors may also have positive effects on tumor-specific T cells." (PMID 28548063, 2014). "Vimentin and CD68 staining in the stromal compartments of CRCs with low and high expression of TLR4 confirmed that the increased TLR4 signal was localized to PCMs and not related to tumor-associated macrophages." (PMID 24887394, 2014). "Activation of the TLR4 signaling pathway of DCs by Ad vectors could assist in the cross-priming of an adaptive tumor antigen-specific immune response." (PMID 28548063, 2014). "Interestingly, when TLR4 and Fas were simultaneously activated, the tumor promoting capabilities of TLR4 were lost, as well as the increased expression of MMP-9, which was necessary for the U87 cell invasion stimulated by LPS alone." (PMID 25411122, 2014).
tumor (continued). "TLR4 pathway inhibition reversed tumor-mediated suppression of both natural killer cell activity as well as T-cell proliferation in vitro and in vivo, resulting in increased tumor latency and survival of tumor-bearing mice." (PMID 24744758, 2014). "On the other hand, we may screen specific anticancer agents such as chemicals or cytokines, which suppress TLR4 expression to reduce inflammation by specifically inhibiting IgG expression, to kill cancer cells by directly injecting them into the tumor body." (PMID 25179302, 2014). "The co-ligation of TLR2 and TLR4 on DCs was recently shown to potentiate their immunogenicity toward a tumor, and our results suggest that this process could be inhibited by GNP10." (PMID 24802102, 2014). "On the one hand, TLR4, as a negative regulator of cancer, inhibits tumor growth and progression." (PMID 25179302, 2014). "In addition, the expressions of these proinflammatory cytokines and TLR4 of tumor tissues from group 4 were significantly decreased after LPS treatment, compared with those from group 2." (PMID 25179302, 2014). "RT-qPCR analysis indicated that the expressions of the proinflammatory cytokines (TNF-α, IL-6, and IL-1β) and TLR4 of tumor tissues from group 2 were markedly increased at mRNA level after LPS treatment, compared with those of group 1 or 3 without LPS treatment." (PMID 25179302, 2014). "In conclusion, we believe that TLR4 is a potent tumor promoter in the intestine." (PMID 23691015, 2013). "In addition, endogenous ligands for TLRs were also identified, including HSP70 and HMGB1, which have been shown to up-regulate TLR2 and TLR4 on tumor cell surfaces and induce tumor progression and metastasis." (PMID 23650534, 2013). "Moreover, HMGB1 passively released from tumor cells interact with TLR4 on DCs, and result in the stimulation, antigen-processing and -presentation in DCs." (PMID 23717436, 2013). "High expression of TLR4 in HNSCC tumor cells in response to inflammatory stimuli has been found to be associated with IRAK4 up-regulation, AKT phosphorylation, NFκB activation and the increased proliferation of tumor cells." (PMID 24302991, 2013). "Furthermore, these data establish a link between dysregulation of gap junctions, tumor promotion, and the influence of TLR4 in an ex vivo model which will facilitate a mechanistic examination of these protective effects at the molecular level." (PMID 25035812, 2013). "In the current study, we query the role of TLR4 as a tumor promoter in the intestine." (PMID 23691015, 2013). "Finally, silencing of TLR4 with RNA interference in xenograft models of CRC decreases the metastatic tumor burden in the liver, supporting a therapeutic potential in targeting TLR4." (PMID 23691015, 2013). "Tumor growth was substantially inhibited in TLR4-KD and CXCR7-KD group in contrast to scrambled siRNA group in the presence of LMW-HA, suggesting that LMW-HA may promote growth of W3-derived PTC model tumors in vivo through TLR4/CXCR7 pathway." (PMID 24363762, 2013). "EDAvidin could also be used to decorate a biotinylated tumor cell to render it more immunogenic allowing its capture by TLR4 expressing DC." (PMID 24093105, 2013). "Consequently, HMGB1 acts through TLR4 expressed in DCs increasing their capability to present antigens of dying tumour cells." (PMID 23551576, 2013). "Although all experimental models of colonic neoplasia are fundamentally imperfect, we feel that over-expression of TLR4 offers insight into whether TLR4 has a distinct role as a tumor initiator and promoter." (PMID 23691015, 2013). "The expression pattern of MyD88 in OSCC tumor tissues was similar to that of TLR4 (p = 0.034)." (PMID 22583829, 2012). "In cancer treatment, the potential role of DAMP recognition and the initiation of adaptive anti-tumor immunity is seen in breast cancer patients with defective TLR-4 signaling who are less able to respond to standard therapy presumably because of a lack in tumor immune eradication." (PMID 22912933, 2012).
tumor (continued). "Triggering of TLR4 by LPS induced tumor promotion by the induction of proliferation, activation of NF-κB, p65 binding to DNA, and resistance to NK cell-mediated cytotoxicity accompanied by the increased production of proinflammatory cytokines (IL-6 and IL-8), VEGF." (PMID 22583829, 2012). "The expression levels of TLR4 and MyD88 in situ were correlated with tumor differentiation." (PMID 22583829, 2012). "miR-21-5p negatively regulates an innate immune receptor, TLR4 (toll-like receptor 4) by targeting the proinflammatory tumor suppressor, PDCD4 (programmed cell death protein 4), as well as directly modulating a key cytokine in immune regulation, IL-12 (interleukin 12)." (PMID 22937080, 2012). "To determine whether TLR4 is important in LPS-induced tumor cell metastasis and EMT, we used adeno-associated virus to express TLR4 in HepG2 cells [See], then pretreated vec-HepG2 and TLR4-HepG2 with LPS." (PMID 22938142, 2012). "Therefore, we suggest that it is primarily the interaction between S100A9 and TLR4 that promotes tumor growth in our studies." (PMID 22470535, 2012). "HMGB1 released from tumor cells binds to TLR4 on DCs, thus contributing to DC activation." (PMID 22891162, 2012). "To directly test whether the S100A9/TLR4/RAGE interaction was important for EL4 tumor growth in vivo we therefore treated EL4 inoculated animals with 30 mg/kg ABR-215050 and compared to control animals." (PMID 22470535, 2012). "Thus, we decided to continue our studies on the effect of S100A9 and TLR4 on tumor growth in the EL4 tumor system." (PMID 22470535, 2012). "If TLR4 is activated on immune cells, it can enhance anti-tumor immunity." (PMID 22110526, 2011). "Functional TLR4 signaling was also demonstrated on human tumor cells." (PMID 22110526, 2011). "Metastases could be the consequence of activation of the TLR4 signaling pathway that results in reduced apoptosis and increased proliferation of metastatic tumor cells." (PMID 22110526, 2011). "CXCR7 mediated by TLR4 modulated tumor cell proliferation and migration." (PMID 22180778, 2011). "TLR4 signaling was shown to be unimpaired and could induce the synthesis of soluble immune mediators that could help the tumor to withstand the immune attack." (PMID 22110526, 2011). "Furthermore, blockade of tumor TLR4 signaling with anti-TLR4 siRNA or with inhibitory TLR4 peptide treatment prolongs the survival of MC26-bearing mice." (PMID 22110526, 2011). "In addition to the direct contribution of epithelial TLR4 signaling to neoplastic development, the contribution of TLR4 signaling to anti-tumor immunity needs to be evaluated in order to establish treatment for CAC." (PMID 24212947, 2011). "The activation of TLR4 expressed on tumor cells may promote tumor growth and resistant of apoptosis." (PMID 20618976, 2010). "Recent independent studies also found a correlation between TLR4 expression and patient survival in adenocarcinomas, although the study was limited to tumor cell expression and the role for these markers in less malignant conditions or other markers of inflammation were not investigated." (PMID 21059221, 2010). "It was recently reported that TLR4/MyD88 signalling drives tumour growth in numerous organs." (PMID 20145615, 2010). "The literature includes examples of TLR4 having both pro-tumor and anti-tumor activities." (PMID 22069563, 2010). "Relatively little is known about the role of TLR4 in tumor growth or response to chemotherapy." (PMID 22069563, 2010). "Previous studies have reported that when tumor cells are stimulated with lipopolysaccharides (LPS), the ligand for TLR4, the proinflammatory factors such as nitric oxide, IL-6 and IL-12 are expected to be released from tumor cells, attracting and activating inflammatory cells." (PMID 20618976, 2010). "TLR4-mediated cancer growth appears to be an important factor in tumor progression." (PMID 20618976, 2010).
tumor (continued). "The demonstration that Paclitaxel can bind to TLR4 and therefore activate NFκB could explain why we observe tumor growth during Paclitaxel treatment." (PMID 19619321, 2009). "Furthermore, LPS-mediated u-PA and u-PAR upregulation and enhanced tumour cell adhesion and invasion was abrogated by TLR-4 blockade using a functional TLR-4-blocking mAb." (PMID 19436306, 2009). "Moreover, an attenuated Salmonella Typhimurium strain has been engineered to produce Vibrio vulnificus flagellin B specifically within tumor tissues in mice, thereby activating M1-like macrophages and suppressing M2-like macrophages through the TLR4 signaling pathway." (PMID 41602751, 2026). "Upon tumor cell damage or death, DAMPs are released and acquire immunogenicity, capable of binding to pattern recognition receptors such as Toll‐like receptor 4 (TLR4) and the purinergic receptor P2X7, promoting inflammation and activation of the innate immune system." (PMID 41560416, 2026). "Besides, it has been demonstrated that hypoxia induced tumor derived exosomal hsa-circ-0048117 could act as a sponge for miR-140 by competing with TLR4 to facilitate the M2 macrophage polarization in esophageal squamous cell carcinoma tumor micro-milieu." (PMID 39928285, 2025). "Whether cells are necrotic or necroptotic, they release HMGB1 as a DAMP in the extracellular milieu, triggering complex signaling through receptors like RAGE and TLR4 that can either activate immune response or paradoxically enhance tumor survival and foster therapy resistance." (PMID 41465435, 2025). "Important to note, however, that in previous studies on tumor-promoting effects of endotoxin-TLR4 signaling, endotoxin was utilized at concentrations known to cause septic shock and surpass by an order of magnitudes the levels that could be reached at setting of “sterile” tumors or reported in ME." (PMID 40868123, 2025). "In addition, elevated levels of TLR4 detected in patients with NSCLC have been correlated with tumor stage and metastasis, supporting the hypothesis for a critical role of TLRs in the onset and progression of NSCLC." (PMID 40025339, 2025). "Based on the established correlation between the TLR-4 signaling pathway and tumor chemotherapy resistance, future research should delve deeper into whether abnormal TLR-4 expression can serve as an independent biomarker for assessing tumor resistance in clinical treatment." (PMID 40404908, 2025). "Additionally, further investigation is needed to elucidate the role of TLR-4 in different tumor subtypes and patient populations, which may enable personalized treatment strategies based on individual TLR-4 expression profiles." (PMID 40404908, 2025). "Similarly, in tumor models, tumor‐associated neutrophils upregulate GZB when stimulated with a cytokine mix (IL‐2, IL‐12, IL‐21) alone or combined with a TLR4 agonist, demonstrating that innate (TLR) and adaptive (cytokine) signals converge to trigger neutrophil GZB production." (PMID 41244336, 2025). "However, compared to other signaling pathways, there is currently a lack of research on how gut microbiota metabolites influence tumorigenesis and tumor progression by regulating the TLR4 signaling pathway, with studies primarily focusing on butyrate and Uro A metabolites in colorectal tumors." (PMID 41048488, 2025). "NET proteases may potentially target tumor cells or stromal receptors to initiate pro-growth cascades; for instance, NE from NETs can interact with TLR4 on cancer cells, activating downstream mechanisms that enhance mitochondrial biogenesis and proliferation in stressed tumor cells." (PMID 41465319, 2025). "Similarly, in tumor cells, the blockade of TLR-4 may lead to the activation of alternative pathways that sustain cell survival and proliferation." (PMID 40404908, 2025).
tumor (continued). "For example, betulinoporol and triterpenoids exert anticancer effects by inhibiting tumor cell proliferation and inducing apoptosis, while polysaccharides such as β-glucans enhance immune function by activating macrophages and regulating the TLR4/NF-κB signaling pathway." (PMID 40699669, 2025). "Notably, TLR4 has been identified as a key player, with its activation leading to the secretion of pro-inflammatory cytokines and growth factors that facilitate tumor cell proliferation and help the tumor evade immune surveillance." (PMID 41419456, 2025). "Toll-like receptor 4 (TLR4) pathways and the NLRP3 inflammasome are aberrantly activated by pollutant components, leading to excessive IL-1β maturation and skewing alveolar macrophages towards a tumor-associated phenotype that supports immune evasion and tumor progression." (PMID 41345682, 2025). "Expression changes of TLR3 and TLR4 in different cancers were basically consistent, which was closely related to multiple roles of TLR3 and TLR4 as pattern recognition receptors in driving tumor-associated inflammatory cascades, activating immunity and even regulating metabolic reprogramming." (PMID 40535567, 2025). "STING/TLR4 co-loaded lipid nanoparticles (immuno-NPs) enable systemic delivery, maintaining payload stability while reducing systemic toxicity, and demonstrate potent efficacy in murine breast cancer models with 50-60% reduction in tumor weight versus vehicle controls." (PMID 40933890, 2025). "Therefore, the TLR4 signaling pathway plays a crucial role in tumorigenesis and tumor progression." (PMID 41048488, 2025). "However, not all studies have proposed inhibiting TLR4 as a cancer treatment; other studies have proposed an alternative strategy involving its stimulation, which has been associated with reduced tumor growth and better prognosis." (PMID 40878805, 2025). "Accordingly, TLR4 may be a useful biomarker for tumor prognosis and metastasis." (PMID 40727443, 2025). "Their role in GMB progression is mostly beneficial: they may enhance tumor growth by activating EGFR or TLR4 signaling in tumor cells, they support immune evasion by forming physical barriers for cytotoxic T cells or NK cells and contribute to treatment resistance by activating survival pathways." (PMID 41208963, 2025). "Additionally, research has shown that the LPS/S100A7/TLR4 signaling pathway may promote tumor growth and metastasis by recruiting MDSCs and weakening TLR4-mediated tumor immunity." (PMID 41597595, 2025). "It has been reported that the TCM Polysaccharides could enhance NK cell cytotoxicity against tumor cells via TLR4/MAPKs/NF-κB pathway, promote the TLR4-dependent production of interferon (IFN)-γ, and upregulate the protein level expression of CD69 in spleen NK cells." (PMID 38455058, 2024). "Interestingly, a lack of or block of TLR4 and a pro-inflammatory cascade has been linked to a better treatment response and prognosis in many tumor types." (PMID 39451550, 2024). "further found that in TLR2 and TLR4 agonist-stimulated monocytes/macrophages and tumor-infiltrating immune cells, tumor cells could secrete lactate to activate the IL-23/IL-17 pathway and promote tumorigenesis and growth by promoting angiogenesis and triggering a local inflammatory response." (PMID 39660139, 2024). "Thus, the conversion of TLR4 activation from antitumor to protumor activity by agonists—which depends on a variety of criteria, including timing, duration, and strength—remains a challenging issue for scientists studying tumor immunotherapy." (PMID 38685971, 2024). "Therefore, targeting TLR4 in TAMs could be an attractive therapeutic strategy to counteract tumor growth in cancer patients." (PMID 38397187, 2024).